EGFR (epidermal growth factor receptor)
Diseases named in the same sentence as EGFR in open-access papers (continued):
Sharing a sentence is not in itself a finding about the gene and the disease.
lung cancer (continued). "On the other hand, EGFR mutant lung cancer is more immunologically “cold,” and while treatment with higher-generation targeted therapy (e.g., Osimertinib) is associated with greater overall survival and improved prognosis, immune checkpoint blockade responsiveness by such tumors is low." (PMID 41479781, 2025). "Therefore, the integration of TCM with conventional therapies, including chemotherapy, EGFR-TKIs, and radiation, holds promise for improving treatment outcomes in lung cancer patients." (PMID 40417000, 2025). "For instance, MET amplification may offer a second growth signal in EGFR-mutant lung cancer treated with EGFR inhibitors." (PMID 40227591, 2025). "Smoking influences lung cancer risk and mutation patterns, while EGFR mutations are more frequent in non-smokers, with prior studies also linking smoking status to serum metabolite profiles." (PMID 41142757, 2025). "In lung cancer, oncogenic mutations in KRAS and EGFR are associated with treatment resistance." (PMID 39781466, 2025). "Mutant EGFR becomes constitutively active and plays an important role in lung cancer pathogenesis." (PMID 40940888, 2025). "In a preclinical study, it was reported that although osimertinib inhibited glycolysis in lung cancer with EGFR mutations, it did not do so in osimertinib-resistant cells." (PMID 40940888, 2025). "The level of exosomal EGFR in lung cancer patients was significantly increased." (PMID 40575159, 2025). "It is important to note, however, that first-line immunotherapy is not recommended for patient groups with genomic-driven lung cancers, such as those with EGFR mutations or ALK-positive NSCLC." (PMID 40075700, 2025). "Moreover, lung cancer cells are known to exhibit a high expression of EGFR, which is located on the cell membrane." (PMID 40141140, 2025). "Unlike tumors driven by recurrent “trunk” mutations (e.g., EGFR in lung cancer), osteosarcoma lacks consistent and targetable mutations." (PMID 41346999, 2025). "This approach has been used to model different mechanisms of EGFR resistance in lung cancer cells." (PMID 40428391, 2025). "Therefore, it can be used as a single drug or in combination with EGFR-TKIs to treat EGFR mutant lung cancer." (PMID 40172117, 2025). "Additionally, in lung organoid models, mannose glycosides have been shown to enhance lung cancer cell sensitivity to EGFR-TKI therapy via the induction of ferroptosis." (PMID 40427552, 2025). "Known lung cancer genes (EGFR, KRAS G12C, ALK, MET, RET) were found in 33 patients; 11 had genes relevant to both lung and other cancers (ERBB2, BRAF V600, NTRK), and 37 had genes typically linked to other malignancies (NF1, PIK3CA, PALB2, FGFR2B, FBX7, RAD51)." (PMID 40244261, 2025). "Herein, the objective of this study was to determine whether tumor microenvironment promoted EGFR-TKI resistance in lung cancer, and to delineate the possible mechanism." (PMID 40703348, 2025). "Although women in Xuanwei are primarily nonsmokers, they nonetheless have a very high incidence of lung cancer with LUAD tumors that harbor EGFR mutations." (PMID 40227422, 2025). "The stability of the EGFR protein has a positive effect on TKI resistance in lung cancer." (PMID 40979592, 2025). "Therefore, targeting the agrin‐EGFR‐YAP rigidity sensing module presents a promising therapeutic strategy for EGFR‐driven lung cancers." (PMID 40165020, 2025). "Therefore, when these studies are extended to human lung cancer cell lines, the expression levels of EGFR, HER2, HER3, and Axl need to be determined and accounted for." (PMID 40649937, 2025). "Furthermore, the epidermal growth factor receptor plays a crucial role in NSC lung cancer, and its activation promotes tumor growth, invasion, and metastasis." (PMID 40329373, 2025).
lung cancer (continued). "Overall, these findings suggest an oncological potential of SMARCB1 as a prognosis biomarker for EGFR-TKI-based therapy responsiveness in lung cancer, uncovering its in vivo function as a tumor suppressor gene and a significant epigenetic actor in human lung cancer progression." (PMID 39971779, 2025). "Interestingly, AXL has been found to influence acquired resistance to EGFR-targeted therapies in both breast and lung cancers." (PMID 39924521, 2025). "Moreover, evidence suggests that patients with EGFR-mutant lung cancer have a higher incidence of MPE than those with wild-type EGFR." (PMID 41479892, 2025). "Additionally, EGFR was found to be significantly overexpressed in lung cancer patients, as validated by the GEO dataset GSE7670, further supporting its role as a core therapeutic target." (PMID 41465428, 2025). "Furthermore, among EGFR TKI‐treated lung cancers, there is little clinical data available on the use of weak (tramadol, codeine, buprenorphine) or strong (morphine, oxycodone, fentanyl, hydromorphone) opioids and their effect on treatment outcomes." (PMID 40650440, 2025). "Lung cancer remains the leading cause of cancer death worldwide, and non-small-cell lung cancer (NSCLC) accounts for approximately 85% of cases, with up to 50% of Asian patients harboring epidermal growth factor receptor (EGFR) mutations." (PMID 41462168, 2025). "Thus, identifying novel therapeutic means or agents for combating EGFR-TKI-resistant lung cancer is of critical importance." (PMID 40872626, 2025). "For instance, we detected key actionable mutations, such as KRAS G12C and EGFR T790M, exclusively in plasma in certain stage III cases, underscoring the importance of combining liquid biopsy with tissue biopsy for more comprehensive lung cancer management." (PMID 40282516, 2025). "Moreover, p-EGFR in lung cancer cells has been identified as a potent CSC biomarker, associated with a strong sensitivity to anti-EGFR agents (e.g., erlotinib) in vitro and in vivo." (PMID 40738059, 2025). "All three of these were newly identified biomarkers for lung cancer and EGFR-TKIs resistance." (PMID 41358202, 2025). "In lung cancer, where actionable alterations such as EGFR, ALK, ROS1, and MET have direct therapeutic implications, optimizing patient selection for NGS testing could further enhance cost-efficiency." (PMID 41301039, 2025). "Therapeutic advances in treatment of lung cancer have included targeted therapies, which are available for patients with mutations in oncogenes such as ROS Proto-Oncogene 1 (ROS1), epidermal growth factor receptor (EGFR), anaplastic lymphoma kinase (ALK), and B-raf proto-oncogene (BRAF)." (PMID 41316207, 2025). "The total dosage divided by the Defined Daily Doses (DDDs) revealed a clear upward trend for nearly all small molecule targeting inhibitors targeting lung cancer, with the exception of Gefitinib, Erlotinib, and Afatinib—representatives of the earlier generations of EGFR-targeted therapies." (PMID 41282618, 2025). "Therefore, we included an additional lung cancer cell line, NCI-H1650, which also carries an EGFR mutation." (PMID 40141140, 2025). "The targeted NPs exhibited higher uptake in EGFR-overexpressing lung cancer cells A549 and NCI-H23." (PMID 39940134, 2025). "Potential YAP/TAZ mediated therapy resistance in EGFR TKI-resistant lung cancer and platinum-resistant ovarian cancer and the impact this has on tumor metabolism as a result of YAP/TAZ controlling tumor mesenchymal stem cells in the hypoxic environment of hepatocellular carcinoma is highlighted." (PMID 40630468, 2025). "Unlike specific EGFR mutations found in lung cancer that determine tumor sensitivity/resistance to the EGFR tyrosine kinase inhibitor gefitinib, such mutations are uncommon in breast cancer cells." (PMID 40560045, 2025).
lung cancer (continued). "Additionally, this regulation involves chromatin remodeling proteins, such as SMARCB1, which binds to EGFR gene regulatory sequences, further shaping its expression and contributing to lung cancer progression." (PMID 39971779, 2025). "For example, German health care claims do not include any information regarding the histological lung cancer subtype as well as PD-L1 expression of the tumor or other genetic mutations such as EGFR or ALK." (PMID 40739492, 2025). "In detail, research has revealed that ginsenoside Rg3 disrupts the cell cycle at G0/G1 phase via the EGFR/Ras/Raf/MEK/ERK pathway in lung cancer (A549), liver cancer (Hep G2) cells, and the formation of Cyclin D1, CDK2, and CDK4 in colon cancer (SW620 and LoVo) cells." (PMID 40490812, 2025). "Moreover, multiple lines of evidence from research suggested that lidocaine inhibited the progression of lung cancer, colorectal cancer and retinoblastoma via regulating EGFR axis." (PMID 39888904, 2025). "The overall results suggest that caffeic acid, a key bioactive compound in M. oleifera, is an EGFR-mediated oncogenic signaling inhibitor for lung cancer therapy, warranting further experimental validation to translate these findings into clinical applications." (PMID 41155483, 2025). "This study further supports the therapeutic potential of furmonertinib in EGFR-mutant lung cancer." (PMID 40963567, 2025). "Nevertheless, higher SMARCB1 expression correlated with significant extended PFIs in TKI-treated early-stage patients compared to lower levels, consistent with studies linking mSWI/SNF subunit alterations to reduced progression-free survival in EGFR-TKI therapy for lung cancer." (PMID 39971779, 2025). "Blood exosomes from 30 breast cancer patients, 30 colorectal cancer patients, 30 lung cancer patients, and 39 healthy controls were collected and quantified for PD-L1, EpCAM, and EGFR, showing that the expression of these genes was increased in cancer patients." (PMID 40075875, 2025). "Reports from prostate cancer suggest polycomb-independent oncogenic functions of EZH2 that converge on AKT activation, and similar EZH2-mediated mechanisms have been linked to resistance to PARP inhibitors in ovarian cancer and to EGFR inhibitors in lung cancer." (PMID 41156200, 2025). "EGFR‐TKI resistance is inevitable in advanced EGFRm lung cancer." (PMID 39994841, 2025). "Patients with metastatic lung cancer harboring epidermal growth factor receptor mutations represent a very relevant subgroup of lung cancer patients because they are never smokers in the majority of the cases and for very good therapeutic outcomes." (PMID 40075694, 2025). "In addition, the majority (72.7%) of late recurrences occurring more than five years after lung cancer surgery have been reported in EGFR-positive non-small-cell lung cancer (NSCLC), highlighting the long-term recurrence potential of EGFR-mutated tumors." (PMID 41416296, 2025). "In our tertiary care centre, the protocol for managing advanced nonsquamous lung cancer patients harboring EGFR-positive mutations involved employing a range of TKIs." (PMID 41333366, 2025). "Notably, the apoptosis-inducing effect of Sp-R-A was significantly enhanced when combined with the clinically approved EGFR-targeting lung cancer drug afatinib, suggesting a potential synergistic effect." (PMID 40430991, 2025). "CXCL8 is associated with resistance to multiple chemotherapeutic approaches including platinum-based drugs in ovarian cancer, epidermal growth factor receptor (EGFR) inhibitors in lung cancer, cisplatin and doxorubicin in hepatocellular carcinoma, and gemcitabine in pancreatic cancer." (PMID 40076892, 2025). "EGFR plays a pivotal role in the pathogenesis of lung cancer, particularly in NSCLC." (PMID 40728967, 2025).
lung cancer (continued). "However, few previous studies have evaluated the impacts of socioeconomic deprivation on outcomes from treatment with erlotinib, gefitinib, or other systemic anticancer therapies in patients with EGFR-mutant or other forms of advanced lung cancer." (PMID 40029742, 2025). "The lung cancer organoid library contained a LADC organoid derived from a smoker that harbored a nonsense mutation (C > A transversion, AA change) in CMTR2 alongside an oncogenic mutation in EGFR." (PMID 41198678, 2025). "Notably, EGFR-mutant lung cancer is characterized by an uninflamed phenotype with a high frequency of inactive tumor-infiltrating lymphocytes (TIL)s, low PD-L1 expression, and low tumor mutation burden." (PMID 40002883, 2025). "Therefore, administration of chemotherapy in eligible patients as the first step prior to the initiation of osimertinib should be considered the standard of care for patients with early-stage EGFR mutant lung cancer after surgical resection." (PMID 41438982, 2025). "Moreover, the combination therapy robustly expelled YAP/TAZ outside the nucleus thereby impacting its association with TEAD transcription, illustrating the importance of agrin–EGFR feedback in potentiating nuclear YAP/TAZ in lung cancers." (PMID 40165020, 2025). "Though ICI discontinued, patient No.4 experienced recurrent liver and kidney dysfunction after chemotherapy following irAE recovery, while one lung cancer patient successfully attempted EGFR targeted therapy after irAE recovery and achieved stable disease without dysfunction of liver and kidney." (PMID 41346594, 2025). "Osimertinib, a third-generation of EGFR-TKI, has been shown to significantly and sustainably increase the expression of both TGF-β1 and αvβ3 integrin in in vitro and in vivo models of EGFR-mutant lung cancer (HCC827 NSCLC cells) with acquired resistance to osimertinib." (PMID 40243917, 2025). "Next, we performed qRT-PCR to validate whether these candidate genes were consistently upregulated more than 2-fold in several EGFR-mutant lung cancer cell lines treated with osimertinib." (PMID 40290805, 2025). "Inhibiting EGFR can significantly disrupt key pathways involved in lung cancer." (PMID 41155483, 2025). "We confirmed that CMTM4 KD reduced EGFR in LLC lung cancer cell line." (PMID 39948411, 2025). "We further screened the candidates showing more than 2-fold upregulation in other lung cancer cell lines, H1975 (L858R and T790 M EGFR mutation) and PC9 (delR746-A750 EGFR mutation) cells treated with 100 nM osimertinib, and identified HDAC5, one of histone deacetylases." (PMID 40290805, 2025). "Furthermore, it was shown that ERK was an essential regulator of the TGFβR and EGFR-mediated signaling pathways and that it was critical for lung cancer cells." (PMID 40142097, 2025). "Although epidermal growth factor receptor (EGFR) inhibitors have revolutionary changes in the treatment landscape of lung cancer, drug resistance remains a formidable clinical challenge, with PTEN alterations emerging as pivotal players in this resistance narrative." (PMID 40129883, 2025). "For example, measuring epidermal growth factor (EGFR) receptors on exosomes could be valuable for in vitro diagnosis, with exosomal EGFR being a potential biomarker for characterizing lung cancer." (PMID 40028522, 2025). "Additionally, network pharmacology and molecular docking studies reveal MA’s interactions with important targets related to lung cancer progression, such as EGFR and SRC, bolstering its potential as a novel anti-lung cancer agent." (PMID 40070571, 2025). "Furthermore, TLR and EGFR signaling pathways are functionally interconnected and synergistically activate NF-κB, which is crucial for lung cancer progression." (PMID 41254241, 2025).
lung cancer (continued). "Although our findings identify IL-35 as a key immunosuppressive cytokine that impairs NK cell function in the EGFR-mutant non–small cell lung cancer (NSCLC) microenvironment, several limitations and potential confounding factors should be acknowledged to ensure proper interpretation of the results." (PMID 41357575, 2025). "In case, without protein immunoprecipitation, the approach identified important glycosylation and phosphorylation on druggable protein, such as 10 of 12 N-glycosylation sites and driver autophosphorylation sites, such as Y1172 and Y1110 of EGFR protein, the druggable target in lung cancer." (PMID 40154885, 2025). "Additionally, while folic acid modification of exosomes provides a degree of targeting specificity due to the overexpression of folate receptors in EGFR-TKI resistant lung cancer cells, more precise targeting strategies should be explored." (PMID 39744423, 2025). "Lung cancer cells are believed to also acquire resistance to EGFR-TKIs via metabolic reprogramming." (PMID 40940888, 2025). "Acquired resistance to epidermal growth factor receptor tyrosine kinase inhibitors (EGFR TKIs) remains a significant hurdle for patients with EGFR‐mutated non‐small cell lung cancer (NSCLC), particularly those lacking the EGFRT790M." (PMID 39715697, 2025). "Moreover, lidocaine suppressed the viability, migration and invasion of lung cancer cells, but induced apoptotic death by blocking EGFR signaling." (PMID 39888904, 2025). "The epidermal growth factor receptor (EGFR), an important transmembrane tyrosine kinase receptor, is often overexpressed or mutated in non-small cell lung cancer (NSCLC), which accounts for 85% of lung cancer." (PMID 40533443, 2025). "A total of 3795 patients were included in the analysis, of which 982 had colorectal cancer with 421 KRAS‐positive cases and 36 NRAS‐positive cases, 1246 had breast cancer with 410 PIK3CA‐positive cases, and 1567 had non‐small cell lung cancer with 300 EGFR‐positive cases." (PMID 40056420, 2025). "In non‐small cell lung cancer (NSCLC) patients resistant to first‐ or second‐generation epidermal growth factor receptor (EGFR) tyrosine kinase inhibitors (TKI), only half develop the T790M mutation and thus qualify for the treatment using third‐generation EGFR‐TKIs." (PMID 41399957, 2025). "In addition, the role of EMT in mediating resistance to EGFR TKIs in EGFR‐mutant lung cancer patients has been extensively researched." (PMID 41415713, 2025). "The EGFR inhibitors used in lung cancer treatment are classified into three generations." (PMID 41282618, 2025). "In addition, analysis of public data (GSE121634) demonstrated increased DKK1 expression in lung cancer cells resistant to another EGFR-TKI, erlotinib, in HCC827 and HCC4006 cells." (PMID 40025612, 2025). "Three of these variants were detectable using Cobas EGFR Mutation Test v2, six variants were detectable using Lung Cancer Compact Panel, and none were detectable using Amoy Dx." (PMID 39947926, 2025). "Although HER2 mutations are not as common as other mutations like EGFR or KRAS in lung cancer, the discovery of effective therapies targeting HER2 mutations has been a breakthrough in lung cancer treatment." (PMID 41180730, 2025). "Furthermore, this review specifically discusses the impact of epidermal growth factor receptor (EGFR) and KRAS mutations on lung cancer progression and the consequent immune escape mechanisms they engender." (PMID 40847555, 2025). "FTO upregulation in EGFR TKI lung cancer cells indicates that FTO could promote tumorigenesis of resistant cells." (PMID 40722726, 2025).